IFNG (interferon gamma)
Diseases named in the same sentence as IFNG in open-access papers (continued):
Sharing a sentence is not in itself a finding about the gene and the disease.
infection (continued). "We found that LGG attenuates the S. Infantis-induced expansion of CD4+ T-bet− IFNγ+ T cells, which could be attributed to the decline in the number of CD4+ IFNγ+T cells in peripheral blood observed 24 h after infection." (PMID 28770173, 2017). "After infection, we found that Zbtb32-/- mice had higher proportions and absolute numbers of LCMV-specific CD8+ T cells at days 8 and 45 post-infection, a result confirmed by ex vivo IFNγ production." (PMID 28827827, 2017). "IFNG-/- mice without CD8 Tm cell transfer were highly susceptible to LM as demonstrated by over 108 CFUs in both the spleen and the liver at 72h post infection." (PMID 29155896, 2017). "In mice depleted of both neutrophils and monocytes with the anti-Gr-1 antibody, we observed a significant and sustained decrease in IFNγ levels in the BALF at 24 and 72 hours post-infection, in agreement with previous studies also using anti-Gr-1 antibody-mediated depletion." (PMID 28384349, 2017). "However, we have previously shown that OTI cells either activated in vivo by infection with HKx31-OVA or in vitro by a 5h peptide stimulation, produce TNF protein prior to IFNγ, which supports the current findings." (PMID 28886201, 2017). "In C57BL/6 adult mice, IFNγ-producing CD4+ T cells were essential in the initial phases of C. parvum infection to control the severity of infection, while IL-4-producing CD4+ T cells were important to accelerate resolution of infection." (PMID 29295550, 2017). "Monocytes were either activated or not with IFNγ 2h prior to infection; cells were kept under hypoxic conditions at all time to mimic the bone marrow and the splenic environment." (PMID 28892492, 2017). "Accordingly, a single intranasal infection with Streptococcus pyrogenes gives rise to Th17 cells that exclusively produce IL-17 without IFNγ co-production, whereas repeated infection results in emergence of IL-17/IFNγ double producers." (PMID 28408906, 2017). "The mRNA concentration of the MAP3K8-encoding gene-a representative of the MAP kinases-was 3.6 fold upregulated in the E. coli infected udders (at 3 h pi) while that of IFNG had not been changed during the udder infections." (PMID 28684793, 2017). "In mice lacking B cells and CD8+ T cells, IFNγ is required for acute infection control, suggesting that it mediates the anti-viral effect of CD4+ T cells." (PMID 28394921, 2017). "IFNγ is critical for controlling L. pneumophila infection, but NK cells do not account for all of the IFNγ produced during infection." (PMID 28384349, 2017). "In C57BL/6 mice NK cells did not make a significant contribution to infection control in lungs at d10, making it unlikely that they were a significant source of IFNγ in this setting." (PMID 28394921, 2017). "Surprisingly, administration of RU486 post infection led to better survival of ISPs in Ifnγ−/− mice, but not BL/6." (PMID 28091621, 2017). "The data clearly showed that adding intranasal immunization to the parenteral immunization led to a strong post-infection increase in both the Th17 (CD4+CD44+IL-17+) and Th1 (CD4+CD44+IFNγ+) response as well the IgA response compared to the pre-infection response." (PMID 28414746, 2017). "In individuals with inflammation in the absence of infection the IFNG/IL22 and NK cell response was reduced, however, pro-inflammatory, growth and matrix factors remained upregulated and mucins were downregulated." (PMID 28966918, 2017). "An international, prospective, randomized double-blind trial in CGD patients showed clear reduction in severe infections in the IFNγ (50 μg/m2 subcutaneously three times weekly) group without exacerbation of granulomatous or inflammatory complications." (PMID 28848545, 2017). "However, only splenocytes from HCMV-infected huBLT mice produced IFNγ in response to stimulation with HCMV lysate, indicating the generation of HCMV-specific T-cells following infection." (PMID 28428537, 2017).
infection (continued). "The authors further show that CD4+ T cells develop into TH17 cells in the infection with R. typhi in the absence of IFNγ." (PMID 28770333, 2017). "There was no indication that IFNγ signalling played a major role regulating the B cell compartment following infection." (PMID 28671989, 2017). "Following infection with L. major (LV39), IL-4−/− or IL-4Rα−/− mice on a BALB/c genetic background were able to control lesion size and the levels of IFNγ present in draining lymph node (dLN) cells was either very low or remained unchanged compared to that observed in BALB/c wild-type mice." (PMID 29067025, 2017). "To test the hypothesis that IFNγ signalling and/or TNFR signalling in LT-HSCs were driving increased proliferation during infection with L. donovani, we established BM mixed chimeras with equal number of total BM cells derived from WT and IFNγR2KO or TNFRdKO." (PMID 28671989, 2017). "Taken together, infection with GAS led to a significant recall response in i.n. vaccinated mice, which was characterized by increased levels of IL-17 producing T cells (and to a slightly lesser degree, IFNγ) as well as increased mucosal levels of IgA." (PMID 28414746, 2017). "Most of the CD46+ pups succumb to the infection between 9–12 dpi regardless of IFNγ expression, and it is unclear why the CD46+ pups would demonstrate a decline in inflammatory signaling pathways when the virus is still present." (PMID 27178303, 2016). "For instance, mice lacking MyD88, the common adaptor protein for many Plasmodium-stimulated TLRs, exhibited diminished blood inflammatory cytokines (IL-6, IL-12, IFNα, IFNγ, TNF, CCL2) in several of the murine models, leading to improved resistance to these infections." (PMID 27792766, 2016). "For example, C3H/HeN mice depleted of either IFNγ or TNFα showed enhanced disease upon infection with a dose of R. conorii that normally does not result in symptomatic disease and similar observations were made for R. typhi infection of C3H/HeN mice." (PMID 27875529, 2016). "We noticed that a comparable percentage of the pp65-CTL became activated as assessed by IFNγ and TNFα intracellular cytokine staining, independent of which virus was used for the infection of DC." (PMID 27907183, 2016). "In LCMV, phenotypic HSCs are reduced early in the course of infection, independent of IFNγ and likely through the actions of type I IFNs." (PMID 27621733, 2016). "Both vaccination and infection induced a rise in E. chaffeensis-specific antibody titers and a significant Th1 response in peripheral blood as measured by E. chaffeensis antigen-dependent CD4+ T cell proliferation and IFNγ production." (PMID 26841025, 2016). "Our data confirm that infection with hrHPV decreases basal STAT1 protein levels in KCs but also show that hrHPV does not interfere with IFNγ-induced STAT1 activation per se, as reflected by STAT1 phosphorylation and increase in RARRES1 and IFITM1 expression." (PMID 27920775, 2016). "Infection with pathogens that induce TH1 CD4+ lymphocytes and secrete interferon gamma (IFNg) and interleukin-2 (IL-2) can be compared to induction of the TH2 response following schistosome infection or exposure to parasite eggs or egg antigen resulting in the production of IL-4, IL-5, and IL-13." (PMID 26741130, 2016). "In spleen, the frequency of IFNγ-producing cNK cells increased after RH and ME49 infections." (PMID 27721814, 2016). "However, significant increases in the transcription of goose IFNα, IFNγ, IL1β, and IL6 were all observed after infection with these two types of virus (TMUV and GPV) (P < 0.01; P < 0.01; P < 0.01; P < 0.01)." (PMID 27150912, 2016). "Moreover, high mRNA levels for the cytokines interferon-γ (IFNγ), interleukin-1β and TNF-α were found in human BU lesions, indicating that the innate immune system is activated at the site of infection." (PMID 26863011, 2016).
infection (continued). "Infection with CIV alone, Sp alone or coinfection stimulated a significantly higher release of cytokines, such as interferon-gamma (IFN)-γ, interleukin 6 (IL)-6, tumor necrosis factor (TNF-α) and lymphotactin (Lptn), than was observed in the mock-infected group (PBS)." (PMID 27259293, 2016). "Several cytokines produced by T cells (IFNγ or TNF35, 36), myeloid cells (IL-1, IL-12, TNF, IL-6 32, 37, 38, 39, 40) or epithelial cells (GM-CSF41) are ascribed crucial roles in host resistance based on the early mortality of knockout mice following infection." (PMID 27819295, 2016). "Both IFNγ expression in CD4+ and CD8+ T cells as well as Granzyme B expression in CD8+ T cells peaked on day seven post infection which was consistent with the expression of CD11a and KLRG1 on CD8+ T cells, demonstrating that these cells were antigen-experienced effector cells." (PMID 27875529, 2016). "Percentages of IFNγ-producing CD4+ and CD8+ T cells were significantly higher in leptin-treated infected mice compared with untreated infected mice after 60 days of infection." (PMID 27114296, 2016). "Monocytes and NK cells as early source of IFNγ might communicate to each other, via MICA-NKG2D interaction, during an innate immune response to infections in humans." (PMID 27816971, 2016). "We compared the capacity of the parasite to replicate and form plaques in fibroblasts after an initial infection in A549 cells primed or not with IFNγ." (PMID 26874079, 2016). "In IFNγ-treated cells, no cytopathic effect was observed throughout the entire period (up to 100 days post-infection)." (PMID 26809031, 2016). "After the first 4 weeks of infection, CD4+ T, CD8+ T and natural killer (NK) cells recover their capacity to produce IFNγ, thus promoting the macrophage microbicidal activity with NO synthesis and control of granuloma formation in liver (see next paragraph) and ultimately parasite burden reduction." (PMID 26969511, 2016). "While all of the ten IFNγ-/- mice displayed strong swelling of the infected foot pads after 5 weeks of infection, no swelling was observed for the ten WT animals." (PMID 26863011, 2016). "Consistent with this, we did not see an IFNγ-dependent impact on total viral RNA present in cells at early times during infection (2 hours), suggesting very early events are not affected by IFNγ treatment." (PMID 26562011, 2015). "Considering the role of NK cell-derived IFNγ in the combat of infections, it is not surprising that some bacteria, including yersiniae, have evolved defense strategies to inhibit NK cell functions." (PMID 26296209, 2015). "The serum concentration of IFNγ, TNFα, IL-10 and IL-6 only started to increase substantially on day 6 post-infection, and no apparent difference was observed in the serum levels of IL-1β." (PMID 25768944, 2015). "Many similarities between the MHV68 model system in IFNγ unresponsive mice and human IPF have been described, including infection and apoptosis of alveolar epithelial cells, type II pneumocyte hyperplasia, epithelial to mesenchymal transition, and M2 macrophage differentiation in the lung." (PMID 26317335, 2015). "Only by day 6 post infection, do CD8 and CD4 T cells become the dominant IFNγ sources." (PMID 26070118, 2015). "Together, these results indicate that infection, IFNγ and TNFα have negative effects on mitochondrial respiration, which is alleviated by IL-4, while IL-6 afforded some protection, but only against loss of complex-IV." (PMID 26481427, 2015). "First, infection clearance is likely a frequent outcome following exposure because only 10–50% of close contacts with TB patients develop a positive tuberculin skin test (TST) and/or interferon gamma release assay (IGRA) after exposure." (PMID 26214306, 2015). "According to our results, IFNG mRNA levels probably provided the keratinocyte with an innate immunity against skin pathogens, independent of the late lymphocyte-derived IFN-γ (adaptive immunity) in an established infection." (PMID 25815330, 2015).
infection (continued). "In addition, a relevant change in the profile of cytokine expression was observed in relation to the acute phase of infection, with IL10 being switched on and IFNγ off." (PMID 25890318, 2015). "Although immunotherapeutic strategies involving the administration of exogenous interferon-gamma is found to be effective in suppressing leishmaniasis, the high production of IL10 during early stage of infection often suppresses its activity, thereby hindering NO production and disease clearance." (PMID 26660865, 2015). "In our study, parasites from 6th or 10th day of culture lead to higher infection indexes than parasites from the 2nd day independent on macrophages were treated or not with IFNγ/LPS." (PMID 25695070, 2015). "Like classical memory CD8+ T cells, VM cells are able to rapidly produce IFNγ during the first stage of an infection, in absence of antigenic recognition." (PMID 25953241, 2015). "Here, we demonstrate that IFNγ blocks EBOV infection of murine peritoneal macrophages and robustly protects mice from fatal EBOV infection when administered as late as 24 hours following infection." (PMID 26562011, 2015). "The up-regulation of IFNγ and IL22 during the infection may participate in the clearance of the infection and the recovery of the epithelial integrity, respectively." (PMID 25890354, 2015). "Altogether, these data support that the effect of IFNγ on astrocyte infection by T. cruzi is not a common biological process, highlighting the importance of the findings herein unveiled." (PMID 25695249, 2015). "It has been suggested that lower expression of TNFα, along with IFNγ, in SUDV infection may contribute to the longer time to death observed in SUDV infection as compared to EBOV." (PMID 26512687, 2015). "Later in infection, CD8+ and to a lesser extent CD4+ T cells become the main IFNγ producers." (PMID 26070118, 2015). "NK cells were the largely preponderant producers of IFNγ and cytotoxic granules throughout the infection, suggesting that the protective role of γδ T cells did not principally rely on either of these two functions." (PMID 25747674, 2015). "However, by 6 and 24 hours after infection, the steady increase in VSV M and L RNA levels in infected M-CSF-stimulated peritoneal macrophages was significantly reduced by IFNγ treatment." (PMID 26562011, 2015). "Th2 cytokines such as IL-5 and IL-10 were found to be increased during the early stages of infection (days 3–4 pi), while Th1 cytokines such as IL-6, IFNγ, and IL-18 did not increase until later in disease (days 6–9 pi)." (PMID 26512687, 2015). "While TNFα treatment of M-CSF-treated peritoneal macrophages did not inhibit EBOV GP/rVSV replication, the addition of IFNγ prevented infection in either BALB/c or C57BL/6 peritoneal macrophages." (PMID 26562011, 2015). "In the only study regarding the phenotype of responding cells during HPAI infection of chickens, employing different methods, the percentage of IFNγ producing CD8 positive cells in the spleen was approximately 50% at day 6 post-infection, falling to an average of 15% at 20 days post-infection." (PMID 25450002, 2015). "The elevated levels of IFNγ, IL6 and IL12 on d7 of infection were mirrored histologically by the presence of haemozoin-containing phagocytes, several immunoblasts (blast T cells) in the peri-arteriolar lymphatic sheath area and B-cell activation (centroblasts) in germinal centres." (PMID 25890318, 2015). "In contrast, mice lacking IL-1β appeared to control the infection in its early stages, but eventually succumbed and were not rescued by administration of IFNγ." (PMID 25768794, 2015). "Similar to our murine macrophages findings, M-CSF-matured hMDMs were highly permissive for EBOV GP/rVSV infection and human IFNγ, but not TNFα, effectively and profoundly blocked the number of cells infected by our recombinant virus." (PMID 26562011, 2015).
infection (continued). "We then compared IFNγ production by CD4+ and CD8+ T cells isolated from the lung, spleen and draining LNs of anti-IL-9-treated and isotype control antibody treated mice at day 7 post-infection." (PMID 25646821, 2015). "Considering that IFNG+TNF is important in the pathogenesis of Listeria and Hepatitis infections, it is likely that these trans-bands harbor genes that modulate the outcome of infection with these and other pathogens." (PMID 26510153, 2015). "The biological mechanism by which IFNγ promotes infection and T. cruzi growth inside astrocytes was not established." (PMID 25695249, 2015). "By day 6 post infection, CD8 and CD4 T cells seemed to become the dominant IFNγ producing cells." (PMID 26070118, 2015). "Further detailed investigation into the cellular source of IFNγ showed that at day 3 post infection, NK cells were the dominant IFNγ producing population in the spleen, while in the liver both NK and NKT cells were the principal IFNγ producing cell populations." (PMID 26070118, 2015). "To do this, we infected wild type mice with H. polygyrus and at six days post-infection, mice were co-infected with P. chabaudi with or without blocking antibodies to IL-12 and IFNγ." (PMID 26147567, 2015). "By two weeks post-infection, there was an increase in both the percentage and absolute number of iNKT cells producing GM-CSF; this was not the case for IFNγ." (PMID 24391492, 2014). "Using an IFN-γ reporter mouse where eYFP is expressed under the IFNG-promoter, we could detect IFN-γ producing cells in the BM 24 h after infection 43 and that the cells that produced IFN-γ change over the first week of infection." (PMID 24825601, 2014). "Specifically, basal production of IFNγ in the absence of infection drives HSC cycling and the elevated levels occurring during infection can activate HSC proliferation and myelopoiesis to replenish monocytes and other immune cells." (PMID 25309533, 2014). "Most of the significantly differentially expressed genes (SDEG) are part of immune cell networks such as tumor necrosis factor-alpha (TNF-α) and interferon-gamma (IFN-γ) regulon, indicating that infection by the mutant mounts a stronger host immune response compared to the wild type." (PMID 25201772, 2014). "Therefore, IFNγ production appears to be an early response to MAP infection and this response continues throughout a persistent infection." (PMID 24885748, 2014). "Additionally, the mice pre-immunized with SGS and subsequently infected with L. braziliensis plus SGS had lower levels of IFNγ to IL-4 ratios compared to mice inoculated with PBS and infected with L. braziliensis plus SGS at 2 weeks post infection." (PMID 24421912, 2014). "Following lethal infection of non-human primates with variola virus, the level of IFN-gamma (IFNγ) increases at the advanced final stages of the disease to about 3 orders of magnitude over the cytokine level in naive animals." (PMID 25350003, 2014). "However, 12 days post infection, Cd28flox/floxOx40cre/+ mice had reduced numbers of CXCR5+Bcl-6+CD4+ Tfh cells and IFNγ+CD44highCD4+ Th1 cells in the medLN and Th1 cells in the lungs compared to control mice." (PMID 25347065, 2014). "This is consistent with in vivo observations, where TNFα, IL-12 and IFNγ serum protein levels were not significantly elevated in B6 miR-146a−/− mice at 4 weeks post-infection, relative to B6 mice." (PMID 24967703, 2014). "While IDO was already induced in monocytic cells upon infection and was further elevated by IFNγ, infected and non-infected endothelial cells required IFNγ stimulation to induce IDO expression." (PMID 25157255, 2014). "Thus, although CD1d-independent GM-CSF and IFNγ was observed in vitro, TCR signaling is crucial in vivo during infection to stimulate iNKT cells to produce cytokines." (PMID 24391492, 2014). "Splenocytes from ST2 deficient mice had no impaired production of IL-4, IL-5, IL-10 or IFNγ following ConA stimulation and this was throughout infection." (PMID 24663956, 2014).